CST3 (cystatin C)
Diseases named in the same sentence as CST3 in open-access papers (continued):
Sharing a sentence is not in itself a finding about the gene and the disease.
bladder cancer (7 papers, 2017 to 2025). "Because of the opposite conclusions in the only studies, there is still great research potential to study the association between cystatin C and bladder cancer." (PMID 36589819, 2022). "Fewer studies have examined the association between cystatin C and bladder cancer." (PMID 36589819, 2022). "Our results revealed that CST1/CST2/CST6 genes were significantly upregulated, whereas CST3/CTS7 genes were downregulated in bladder cancers." (PMID 40747123, 2025). "Further studies are necessary to investigate the clinical utility of cystatin C in bladder cancer." (PMID 28977873, 2017). "In addition, some studies have shown that decreased serum cystatin C levels may be present in bladder cancer." (PMID 38779086, 2024). "The findings suggest that serum cystatin C may be used as a potential biomarker for bladder cancer." (PMID 36589819, 2022). "CST6, CSTA, and CSTB were upregulated, while CST3 and CST7 were downregulated in bladder cancer tissues." (PMID 40747123, 2025). "In this study, our results from benign bladder tissues and cancer cell lines showed that CST3, CST6, CSTA, and CSTB were the predominant isoforms out of the 14 family members expressed by bladder cancer cells." (PMID 40747123, 2025). "In bladder cancer tissues, CST1, CST2, CST6, CSTA, and CSTB were significantly upregulated, while CST3 and CST7 were downregulated compared to benign tissues." (PMID 40747123, 2025). "The authors found that circulating cystatin C is neither a reliable predictor of bladder cancer clinicopathologic characteristics nor a possible predictor of bladder cancer carcinogenesis." (PMID 36589819, 2022). "A study published in 2006 indicates that cystatin C concentrations are not directly correlated with the progression of primary bladder carcinomas." (PMID 29789781, 2018). "However, no study has evaluated the impact of cystatin C on prognosis in bladder cancer patients." (PMID 28977873, 2017).
cerebrovascular disease (7 papers, 2017 to 2023). "Similar function of CST3 could be important in cerebrovascular disease pathology." (PMID 32170118, 2020).
fibrosis (7 papers, 2016 to 2026). the formation of excess fibrous connective tissue in an organ or tissue in a reparative or reactive process. "Fibronectin and PC-III are routine markers of fibrosis, and Cystatin C is commonly used to evaluate glomerular filtration function." (PMID 30279506, 2018). "Scr, BUN, Cystatin C, and 24‐h proteinuria levels were greater in the moderate–severe fibrosis group than in the no fibrosis–mild fibrosis group, while the eGFR was lower in the moderate–severe fibrosis group (p < 0.001)." (PMID 39799463, 2025). "We aimed to investigate the value of serum creatinine-to-cystatin C ratio (CCR) in evaluating these two parameters and predicting liver steatosis and fibrosis." (PMID 33935810, 2021).
frontotemporal dementia (7 papers, 2011 to 2023). Frontotemporal dementia (FTD) comprises a group of neurodegenerative disorders, characterized by progressive changes in behavior, executive dysfunction and language impairment, as a result of degeneration of the medial prefrontal and frontoinsular cortices. "Genetically, the CST3 B haplotype of cystatin C was considered to be a risk factor for AD, frontotemporal dementia, and Lewy body dementia." (PMID 37207178, 2023). "Genetically, the CST3 B haplotype of cystatin C was considered to be a risk factor for AD, frontotemporal dementia (FTD), and Lewy body dementia (LBD)." (PMID 35153722, 2021).
glioblastoma (7 papers, 2004 to 2025). The most malignant astrocytic tumor (WHO grade IV). "Cystatin C was shown to be implicated in the invasiveness of human glioblastoma cells and as a result, sense transcripts of cystatin C may prove useful in cancer therapy." (PMID 23984285, 2013). "The cystatin C gene is located at the extracellular region of the cell and has role in invasiveness of human glioblastoma cells." (PMID 23777239, 2013). "In human glioblastoma cells, inverse correlation between cystatin C and tumour grade was observed." (PMID 15138478, 2004).
ischemia (7 papers, 2011 to 2022). A hypoperfusion of the BLOOD through an organ or tissue caused by a PATHOLOGIC CONSTRICTION or obstruction of its BLOOD VESSELS, or an absence of BLOOD CIRCULATION. "When the individual delta (difference between pre-transplant and 8-h reperfusion sample) was calculated, a significantly smaller ischemia-associated rise of the cystatin C serum levels in the Bryostatin-1-treated group was found." (PMID 35326400, 2022). "Megalin is essential for the normal tubular recovery of endogenous cystatin C. The increase in urinary cystatin C excretion after ischemia/reperfusion injury is associated with decreased tubular uptake but not with reduced megalin expression." (PMID 28575050, 2017). "It has been recognized that hs-CRP and cystatin C are markers of inflammation and that cystatin C is associated with ischemia." (PMID 21857933, 2011). "Univariate and multivariable regression analyses of renalase, BNP, cystatin C and biomarkers of myocardial remodeling for prediction of ischemia in the chronic HF patients." (PMID 34395559, 2021). "The variation of CST3 expression level may link with different types of CoW in our inbred strain of ischemia-prone Mongolian gerbils." (PMID 32733872, 2020). "In our inbred strain of ischemia-prone Mongolian gerbils, Cst3 was identified as one of the differential expression (DE) genes, which may link with different types of CoW." (PMID 32733872, 2020). "Whereas native SECR or SECR/MV in combination did not improve kidney function after ischemia (671 ± 26 and 630 ± 25 vs. 696 ± 26 ng/ml; p=0.5 and p=0.08), MV derived from unstimulated cells significantly lowered serum cystatin C levels (593 ± 17 vs. 696 ± 26 ng/ml; p=0.004)." (PMID 33777453, 2021).
kidney stones (7 papers, 2020 to 2025). "We report marked differences in the use of confirmatory kidney function testing (eGFR, creatinine/cystatin C, mGFR, creatinine clearance), albuminuria assessment, and the acceptance policy of donors with nephrolithiasis." (PMID 40735507, 2025). "Univariate logistic analysis revealed that creatinine, cystatin C, Apo B, LDL-C, and TC were high risk factors for kidney stone recurrence among those with BMI ≥ 25 kg/m2, while eGFR was a protective factor." (PMID 37742017, 2023). "The results of the study revealed that creatinine, cystatin C, TC, LDL-C, and Apo B expressions were higher in the kidney stone recurrence group than non-recurrence group, and eGFR values were lower than in the stone non-recurrence group." (PMID 37742017, 2023).
leukemia (7 papers, 2012 to 2025). A malignant (clonal) hematologic disorder, involving hematopoietic stem cells and characterized by the presence of primitive or atypical myeloid or lymphoid cells in the bone marrow and the blood. "In the present paper, we have studied three different tumor‐derived epithelial cell lines and observed that externally added cystatin C caused a reduction in cell numbers, similar to its effect on leukemia cells." (PMID 33837649, 2021). "CST3 has been identified as a biologically relevant gene in the context of leukemia, and it has also been noted as one of the up-regulated genes in patient/donor pairs with AML." (PMID 40338916, 2025). "We recently observed a dose‐dependent decrease in viability when cystatin C was added to the medium of U937, Jurkat, and HL‐60 leukemia cell cultures." (PMID 33837649, 2021). "For the leukemia dataset, among the 10 top-ranked genes, two genes (ZYX and CCND3) are cancer ones, five (APLP2, CD33, SP3, CD63, PSME1) and one other genes (CST3) are directly or indirectly associated with cancer genes, respectively." (PMID 22830977, 2012). "CST3 was selected in the Top 10 ranked informative genes from the leukaemia dataset." (PMID 40338916, 2025). "However, intrinsic antagonism such as serine/cysteine protease inhibitors Spi2A and Cystatin C prevented downstream effectors from triggering leukemia cells, which were only on the “verge of apoptosis”." (PMID 26716897, 2016).
liver cirrhosis (7 papers, 2013 to 2026). "On the other hand, there is a scarcity of data about the predictive role of serum cystatin C in the recovery of AKI in patients with liver cirrhosis." (PMID 40707908, 2025). "In the current study, higher serum cystatin C levels at admission were found to be a significant predictor of renal recovery in patients with liver cirrhosis." (PMID 40707908, 2025). "Thus, the aim of the current study was to investigate the predictive efficacy of serum cystatin C for the recovery of kidney functions and mortality in hospitalized patients with liver cirrhosis and AKI." (PMID 40707908, 2025). "This is a retrospective study that aimed to investigate the association between baseline serum creatinine and cystatin C levels with the outcomes in the form of in-hospital mortality and recovery of kidney functions in hospitalized patients with AKI and liver cirrhosis." (PMID 40707908, 2025). "Thus, peak serum cystatin C levels were used and identified as a significant predictor of in hospital mortality in patients with liver cirrhosis." (PMID 40707908, 2025). "Moreover, serum cystatin C may offer superior predictive capabilities compared to serum creatinine for assessing the outcome of AKI in patients with liver cirrhosis." (PMID 40707908, 2025). "In addition, studies concluded that serum cystatin C might be an early predictor of AKI development in patients with liver cirrhosis." (PMID 40707908, 2025). "In the current study, baseline serum cystatin C is a predictor of renal recovery in patients with AKI and liver cirrhosis." (PMID 40707908, 2025). "In conclusion, this study demonstrates that peak serum cystatin C levels predict in-hospital mortality in hospitalized patients with AKI and liver cirrhosis." (PMID 40707908, 2025). "This was a retrospective single center study that included hospitalized patients with liver cirrhosis who developed or were admitted with AKI and had serum cystatin C in their records from May 2017 to May 2023." (PMID 40707908, 2025).
obstructive sleep apnea (7 papers, 2016 to 2025). "This study investigates the association between blood cystatin-C (Cys-C) and monocyte-to-high-density lipoprotein cholesterol ratio (MHR), both established inflammatory markers, with the severity of obstructive sleep apnea (OSA) in male patients." (PMID 40166599, 2025). "Finally, 8 studies that matched the inclusion criteria were included, and the relationship between obstructive sleep apnea syndrome and serum cystatin C was analyzed." (PMID 39048772, 2025). "Background and Aims: To investigate the association between obstructive sleep apnea (OSA) severity and baseline serum cystatin C (Cys-C) concentration and to explore the association between baseline serum Cys-C and long-term cardiovascular outcomes and mortality in older patients with OSA." (PMID 36117703, 2022). "In participants without severe obstructive sleep apnea, the morning cystatin C level (0.84 ± 0.11 mg/L) was significantly higher than the evening cystatin C level (0.81 ± 0.11 mg/L) (P = 0.005)." (PMID 38287274, 2024). "With severe obstructive sleep apnea, the cystatin C levels were not different between the morning (0.85 ± 0.11 mg/L) and the evening (0.85 ± 0.10 mg/L)." (PMID 38287274, 2024). "Cystatin C level was increased in the morning in participants without severe obstructive sleep apnea, but not in participants with severe obstructive sleep apnea." (PMID 38287274, 2024).
prediabetes (7 papers, 2014 to 2025). "Elevated cystatin C serum concentration was also described as a risk factor for other disease conditions, such as cardiovascular disease and progression to prediabetes." (PMID 32049341, 2020). "Furthermore, cystatin C has been associated with prediabetes and cardiovascular disease, independent of renal function." (PMID 24498934, 2014).
Abdominal obesity (6 papers, 2016 to 2025). Excessive fat around the stomach and abdomen. "Our study demonstrated that abdominal obesity, as determined by waist circumference, was correlated with cystatin C." (PMID 33129312, 2020). "In this cross-sectional study performed with 1032 community-dwelling adults, older age, male gender, lack of physical activity, low HDL cholesterol, abdominal obesity, high hs-CRP, and high ACR were associated with increased cystatin C levels." (PMID 33129312, 2020). "An increased cystatin C level was significantly associated with older age, male gender, lack of physical activity, low HDL cholesterol, abdominal obesity, high hs-CRP, and high ACR." (PMID 33129312, 2020). "In a cross-sectional study on 1032 community-living Taiwanese adults, older age, male gender, lack of physical activity, low HDL cholesterol, abdominal obesity, high hs-CRP, and high ACR were independently linked with a high cystatin C level." (PMID 33129312, 2020). "Lack of physical activity, low HDL, abdominal obesity, high hs-CRP, and high ACR were the determinants of cystatin C." (PMID 33129312, 2020).
arteriosclerosis (6 papers, 2013 to 2024). A vascular disorder characterized by thickening and hardening of the walls of the arteries. "The association between cystatin C and arteriosclerosis in adults residing in the community has been rarely discussed." (PMID 33129312, 2020). "The association between cystatin C and arteriosclerosis in middle-aged adults has been less consistent." (PMID 33129312, 2020). "Therefore, increased serum cystatin C levels could be related to the progression of arteriosclerosis plaque." (PMID 35307027, 2022).
cerebral amyloid angiopathy (6 papers, 2019 to 2025). "It is interesting that CST3 is associated with NVEPs because this protein is linked to serious pathophysiology, including cerebral amyloid angiopathy, macular degeneration, and age-related macular degeneration-11 (ARMD11)." (PMID 41301405, 2025). "The mutation in Cst3 (Cystatin C) has been revealed to be associated with cerebral amyloid angiopathy and Aβ pathway." (PMID 31767948, 2019). "Furthermore, CST3, a basic protein that inhibits cysteine proteases implicated in cerebral amyloid angiopathy and neuroprotective in TBI, was identified in both SCI positive and SCI negative groups (average SC = 7.2)." (PMID 33915030, 2021). "CST3 is also shown to be aggregated in diseases such as cerebral amyloid angiopathy (CAA), where it is deposited on the vessel walls along with Aβ peptide, leading to brain hemorrhage and stroke." (PMID 34575849, 2021). "Cystatin C (CST3) is an endogenous cysteine protease inhibitor, which is implicated in cerebral amyloid angiopathy (CAA)." (PMID 34575849, 2021). "We hypothesized that CST3 plays a crucial role in the development of T2D-induced AD pathology through the regulation of cerebral amyloid angiopathy and insulin signaling in a dose dependent manner." (PMID 37342358, 2023).
cerebral infarction (6 papers, 2013 to 2025). An ischemic condition of the brain, producing a persistent focal neurological deficit in the area of distribution of the cerebral arteries. "In studies of small arteriopathies, cystatin C also showed a strong association with white mater lesions or silent brain infarctions compared to estimated GFR." (PMID 24925313, 2014). "In addition, cystatin C levels have been shown to correlate with silent cerebral infarctions and white matter lesions." (PMID 24925313, 2014).
cerebral small vessel disease (6 papers, 2020 to 2026). Cerebral small vessel disease is the term currently used to pathological processes that affect the brain parenchymal circulation (arterioles, capillaries, and veins). "In a community-based population, the authors reported the association between serum cystatin C and cerebral small vessel disease." (PMID 38681764, 2024). "It remains unclear whether the difference between the estimated glomerular filtration rate based on cystatin C and creatinine (eGFRdiff) is associated with cerebral small vessel disease (CSVD)." (PMID 40280803, 2025). "In addition, the precise balance of CST3 and proteases is essential for vessel remodeling, and polymorphisms in the gene that alter CST3 levels are found to be associated with pathology such as cerebral small vessel disease." (PMID 34575849, 2021). "Nevertheless, we had a concern that CST3 polymorphism affects atherosclerotic lesions, which might change cerebral small vessel diseases pathology indirectly." (PMID 32170118, 2020). "Previous studies have demonstrated that both increased and decreased CST3 levels seem to increase cerebral small vessel diseases pathology." (PMID 32170118, 2020). "Taken together, these findings suggest a relation of cerebral small vessel disease and the alteration of CST3 expression due to polymorphism that is independent of kidney-mediated clearance." (PMID 32170118, 2020).